DLEU2 (deleted in lymphocytic leukemia 2)
Diseases named in the same sentence as DLEU2 in open-access papers (continued):
Sharing a sentence is not in itself a finding about the gene and the disease.
tumor (continued). "In patients with LSCC, high expression of DLEU2 is associated with TNM and tumor stages." (PMID 37095423, 2023). "Transfection of the DLEU2 plasmid in CLL resulted in rapid upregulation of miR-15a and miR-16-1, and overexpression of DLEU2 negatively regulated cyclin E1 and D1 in an miR-15a/miR-16-1 dependent manner, and inhibited proliferation and colony formation of tumor cells." (PMID 37095423, 2023). "In previous studies, DLEU2 was often related to cell proliferation and tumor progression." (PMID 36188540, 2022). "DLEU2 expression was also found to be markedly associated with molecular markers of different tumour-infiltrating immune cell subtypes, such as CD8+ T cell markers, thus it appears that DLEU2 may modulate immune infiltration." (PMID 36614082, 2022). "The results of other studies also demonstrated that DLEU2 expression could stimulate tumour growth, spreading, and invasion in various types of cancers." (PMID 36614082, 2022). "DLEU2 acts as a tumor suppressor by negatively regulating the progression through the cell cycle." (PMID 36362925, 2022). "Besides DLEU1 and DLEU2, tumor-suppressor mechanisms at 13q14.3 involve several protein-coding tumor suppressor genes and pathogenesis of CLL probably results from concerted action of these elements." (PMID 36362925, 2022). "Indeed, it has been demonstrated that DLEU1 and DLEU2 and their neighboring tumor-suppressor genes are epigenetically deregulated in the majority of CLL patients." (PMID 36362925, 2022). "However, DLEU2 knockdown remarkably suppressed tumor growth, as indicated by a decreased tumor volume and weight, and inhibited tumor proliferation." (PMID 32555190, 2020). "In addition, an elevated DLEU2 expression promotes tumor aggressiveness by regulating the miR-455/SMAD2 axis in pancreatic cancer." (PMID 32555190, 2020). "hsa-miR-30-5p regulated DLEU2 and is a tumor suppressor in GC." (PMID 29912172, 2018). "In addition, DLEU2 was the host gene of miR-15a and miR-16-1 which were important tumor suppressors." (PMID 27634882, 2016). "DLEU2 is thought to be a tumor-suppressor gene as it is frequently deleted in malignant tumours." (PMID 25822729, 2015). "In addition, the expression of these six candidate lncRNAs in HCC and nontumor tissues in other GEO RNA‐sequencing datasets (GSE77314, GSE94660, and GSE124535) confirmed the higher expression of most candidate lncRNAs in tumor tissues, save for DLEU2 and NEAT1 in GSE77314 and NEAT1 in GSE94660." (PMID 34185961, 2021). "Furthermore, lncRNA DLEU2 harboured a negative correlation with miR‐30a‐5p expression in NSCLC tissues and acted as a sponge of miR‐30a‐5p, which reversed the tumour‐promoting effects of lncRNA DLEU2 by targeting putative homeodomain transcription factor 2 in NSCLC." (PMID 31721438, 2020). "In CRC, AP4 directly inhibits the transcription of the miR-15a/16-1 host gene DLEU2, leading to the downregulation of DLEU2 and miR-15a/16-1 expression, thereby promoting EMT and tumor metastasis." (PMID 37095423, 2023). "In PC, DLEU2 silencing inhibits SMAD2 by upregulating miR-455 and reducing tumor cell proliferation." (PMID 37095423, 2023). "In our study, the oncogenic roles of DLEU2 and RAP1B in OC and the tumor suppressor role of miR-30a-5p were first determined." (PMID 36277988, 2022). "In vitro, knockdown of lncRNA DLEU2 inhibited proliferation, invasion, migration and induced apoptosis of both A549 and LLC cells; In vivo, it suppressed tumor growth and metastasis." (PMID 31541993, 2019).
tumor (continued). "Furthermore, DLEU2 silencing was observed to suppress NSCLC progression, while DLEU2 overexpression attenuated the anti-tumor effects of Huaier in NSCLC, thereby promoting cell viability, migration and invasion of NSCLC." (PMID 38169645, 2024). "Although the pathways by which DLEU2 promotes the function of malignant tumor cells are not consistent, most have one thing in common: the ceRNA mechanism." (PMID 37095423, 2023). "Therefore, DLEU2 plays an important role in regulating EMT and eliminating intrinsic tumor targets can improve patient survival rates." (PMID 37095423, 2023). "The results showed that DLEU2 and LINC00115 were markedly overexpressed in ccRCC samples compared with normal tissues, whereas the expression levels of COL18A1-AS1 and SNHG10 were remarkably lower in tumor tissues than those in the adjacent non-tumor samples." (PMID 34721523, 2021). "Serum small EV‐derived MALAT1, DLEU2, HOTTIP, and SNHG1 were significantly highly expressed in patients with HCC and showed good to excellent discriminating capacity that was significantly higher than that of the traditional tumor marker AFP." (PMID 34185961, 2021). "Herein, the expression of lncRNA DLEU2 was elevated in NSCLC tissues, and its high expression or low expression of miR‐30a‐5p acted as an independent prognostic factor of poor survival and tumour recurrence in NSCLC." (PMID 31721438, 2020). "Moreover, compared with the tumors overexpressing DLEU2 only, tumors with both DLEU2 overexpression and PIK3CD knockdown showed suppressed tumor growth, decreased tumor volume and weight, and inhibited proliferation." (PMID 32555190, 2020). "Consequently, increased expression of circ-DLEU2 facilitated the in vitro proliferation of leukemic cells, blocked apoptosis, and promoted the formation of AML tumor in vivo." (PMID 31781482, 2019). "Tumor tissues from the remaining 35 enrolled patients (20 radiosensitive patients and 15 radioresistant patients, respectively) were collected to detect the expression of the lncRNAs CASC2, FAM201A, DLEU2, DLX6-AS1, and MCF2L-AS1 by RT-qPCR." (PMID 30574162, 2018). "However, the mechanism of action of DLEU2 in tumor EMT is not completely clear, and further research is needed." (PMID 37095423, 2023). "Furthermore, we detected DLEU2 expression in 45 matched pairs of CRC samples and adjacent non-tumor tissues, and our results indicated that DLEU2 was more highly expressed in CRC tissues than in the adjacent non-tumor tissues (p < 0.05)." (PMID 33391439, 2021). "Thus, interactions between DLEU2, miR-30a-5p and ZEB2 may be biologically significant in the network regulating ccRCC tumor aggressiveness." (PMID 28569782, 2017).
cancer (40 papers, 2014 to 2025). A tumor composed of atypical neoplastic, often pleomorphic cells that invade other tissues. "LncRNA deleted in lymphocytic leukemia 2 (DLEU2) is implicated in the development of various cancers." (PMID 40226549, 2025). "PRANCR and DLEU2 were also down-regulated and are associated with cell proliferation and cancer progression." (PMID 37624890, 2023). "Among the 12 prognostic m6A modification-related lncRNAs included in the m6A-RLPS, DLEU2 has been associated with the prognosis of multiple types of cancers." (PMID 34721523, 2021). "The abnormal expression of DLEU2 in specific tumors distinguishes pathological tissues from normal tissues, suggesting that DLEU2 may be a potentially useful diagnostic biomarker in cancer." (PMID 37095423, 2023). "Evidence suggests that DLEU2 promotes critical tumor traits such as proliferation, migration, invasion, along with resistance to apoptosis in various cancers." (PMID 40226549, 2025). "Among oncogenic lncRNAs deleted in lymphocytic leukemia 2 (DLEU2) is emerging as a key regulator in cancer progression." (PMID 40226549, 2025). "In this study, DLEU2 was identified as a sponge for miR-103a-2-5p, a multifunctional miRNA with context-dependent roles in cancer." (PMID 40226549, 2025). "Currently, studies on the distribution of DLEU2 in cancer cells and its ability to directly bind to and regulate downstream proteins are limited." (PMID 37095423, 2023). "Abnormal DLEU2 expression in cancer cells regulates the occurrence and development of tumors through a ceRNA mechanism, suggesting that DLEU2 is a potential therapeutic target." (PMID 37095423, 2023). "DLEU2 has been verified as a proliferation-inducing lncRNA in the vast majority of cancer types (13 out of 16), and TMPO-AS1 has a role in tumorigenesis and progression and is overexpressed in 15 different cancer types." (PMID 35695878, 2022). "Recent studies suggest that DLEU2 plays a critical role in the development and progression of human cancers." (PMID 33391439, 2021). "As competitive endogenous RNAs sponge miRNAs, the cancer-related functions of DLEU2 are closely related to the transcription of its intronic miRNAs41." (PMID 32555190, 2020). "Aberrant expression of DLEU2 has been frequently identified in cancers and plays crucial roles in the modulation of multiple oncogenic properties." (PMID 32555190, 2020). "Perhaps lncRNA DLEU2 was involved in the development of malignant tumors by targeting downstream genes or mediating signaling pathways, but this mechanism is not yet clear." (PMID 31541993, 2019). "Then, we determined three lncRNAs (RP5-1120P11, DLEU2, and DDX11-AS1) as hub lncRNAs, in which associated ceRNA subnetworks were involved in cell cycle-related processes and cancer-related pathways." (PMID 29912172, 2018). "The DLEU2 locus and embedded miRNA cluster miR-15a/16-1 is commonly deleted in adult cancers and shown to induce leukaemogenesis, however in paediatric AML we found the region to be transcriptionally repressed." (PMID 24885794, 2014). "The lncRNAs DLEU1 and DLEU2 at 13q14.3 are often deleted in multiple types of cancers, and DLEU1 and DLEU2 modulate nuclear factor B function by down-regulating the transcription of their neighboring protein-coding KPNA3 and the microRNAs miR-15 and miR-16." (PMID 24586304, 2014). "These included the cancer-related lncRNAs DLEU2, SNHG7, and LINC01554 (found in only polysomal and common fractions, respectively), the recently re-annotated lncRNA ENS00000269825 (common), the novel lncRNA ENS00000267882 (only total), and the lncRNA DANCR (common)." (PMID 38396700, 2024). "Emerging evidence suggests that DLEU2 may disrupt miRNA function and their interplay is involved in the regulation of numerous types of cancer." (PMID 38169645, 2024). "In summary, DLEU2 is a promising biomarker for cancer diagnosis, prognosis, and treatment." (PMID 37095423, 2023). "In vitro, DLEU2 knockdown inhibited cancer cell proliferation and induced apoptosis." (PMID 37095423, 2023).
cancer (continued). "More recently, DLEU2 has been reported to be abnormally expressed in many malignant tumors." (PMID 37095423, 2023). "DLEU2 is another long noncoding RNA whose aberrant expression was observed in various cancers." (PMID 36614082, 2022). "Importantly, we found that the expression of E2F2, which is known to be dysregulated in various cancers, was significantly related to DLEU2 expression." (PMID 35075115, 2022). "In various cancers, DLEU2 plays a promoting regulatory role in a variety of cancers." (PMID 36277988, 2022). "Additionally, dysregulation of lncRNA DLEU2 plays an important role in regulating the growth and metastasis of human cancer, such as pancreatic ductal adenocarcinoma, lung adenocarcinoma, hematopoietic malignancies." (PMID 31541993, 2019). "Moreover, DLEU2 exhibited high expression levels in primary lung tumors and cancer cells." (PMID 38169645, 2024). "Notably, DLEU2 expression also differed within the same cancer." (PMID 37095423, 2023). "In liver cancer caused by hepatitis B, HBX competes with EZH2 to bind to DLEU2, forming a complex that binds to the TRIMB/CCNB2 promoter, thereby promoting the replication and transcription of covalently closed circular DNA (cccDNA) and promoting cancer progression." (PMID 37095423, 2023). "In addition, DLEU2, as a ceRNA, plays a role in phagocytosing miRNAs in cancer." (PMID 36277988, 2022). "Moreover, we found that treatment with the p38-specific agonist Dehydrocorydaline restored the proliferation, whereas suppressed the apoptosis of cancer cells induced by DLEU2 knockdown, which confirmed that the DLEU2/RARB axis regulates CRC tumorigenesis by manipulating the MAPK signaling pathway." (PMID 35611845, 2022). "Furthermore, HBx and DLEU2 could coregulate a subset of host cancer-related genes to promote hepatocytes transformation." (PMID 34456908, 2021). "Furthermore, DLEU2 exerts a cancer-promoting function by regulating the expression of ETS2." (PMID 34261460, 2021). "We found that a total of 99 lncRNAs appeared in at least two cancer types, and ~74% of them were confirmed as known cancer-related lncRNAs, such as MAGI1-IT1, PTOV1-AS1, and DLEU2." (PMID 39602828, 2024). "We also show the unique role of the lncRNA DLEU2/ROR1 pathway in promoting the EMT and cancer stemness behavior via a mechanism closely engaging with TGF-β signaling, which drives EMT and CSC phenotypes via ALDH1 and BMI1 activation." (PMID 38296962, 2024). "Given that ROR1 signaling actively contributes to the maintenance, self-renewal, and chemoresistance of cancer cells, this raises the possibility that there is a link between ROR1 and the lncRNA DLEU2 pathway and that this pathway regulates CSC behavior." (PMID 38296962, 2024). "DLEU2, HOTTIP, and SNHG1 have also been reported as onco-lncRNAs in HCC, while LINC00853 is currently poorly understood for the role in cancer and deserved for further study." (PMID 37006626, 2023). "Excessive RAP1B promotes cancer cell development, elevates p38 MAPK phosphorylation levels, and reverses the effects of si-DLEU2 on OC cells." (PMID 36277988, 2022). "In this work, we identified the high-expression pattern of DLEU2 in CRC cell lines compared to normal FHC cells, and the DLEU2 knockdown in cancer cells suppressed proliferation, invasiveness, and resistance to death of cells." (PMID 35611845, 2022). "Finally, six lncRNAs (DLEU2, HOTTIP, MALAT1, NEAT1, SNHG1, and TUG1), registered in Lnc2Cancer 2.0, a database offering comprehensive experimentally supported associations between lncRNA and human cancer, were selected as candidate lncRNAs for the diagnosis of HCC." (PMID 34185961, 2021). "By constructing and functionally analyzing lncRNA-associated network, we identified that three hub lncRNAs (RP5-1120P11, DLEU2, and DDX11-AS1) that are involved in cell cycle-related processes and cancer-related pathways." (PMID 29912172, 2018).
cancer (continued). "By reconstructing and functionally analyzing the hub lncRNA-associated subnetworks, we identified three hub lncRNAs (RP5-1120P11, DLEU2, and DDX11-AS1) that are involved in cell cycle-related processes and cancer-related pathways." (PMID 29912172, 2018). "By reconstructing and functionally analyzing each hub lncRNA-associated subnetworks, we identified that three hub lncRNAs (RP5-1120P11, DLEU2, and DDX11-AS1) are involved in cell cycle related processes and cancer-related pathways." (PMID 29912172, 2018). "The results showed that tens of lncRNAs, including cancer-related lncRNAs TUG1, DLEU2, and GAS5, were bound by at least two of the three RBPs at identical binding sites." (PMID 25642422, 2014). "As a known oncogene, lncRNA deleted in lymphocytic leukemia 2 (DLEU2) plays a role in promoting cancer development in most cancers, but the molecular mechanism in OC has not yet been reported." (PMID 36277988, 2022). "The HBx-DLEU2 interaction could replace EZH2 from chromatin, leading to active viral replication and host cancer-related gene transcription." (PMID 34456908, 2021). "Furthermore, in our SMLN, TSA could also upregulate DLEU2 (log2 fold change = 1.4), suggesting that our SMLN could identify a promising cancer therapy via targeting lncRNAs." (PMID 31852840, 2019).
DLEU2 also shares sentences with these, for which no sentence is quoted: acute myeloid leukemia (3 papers); cervical cancer (3); bladder cancer (2); esophageal adenocarcinoma (2); osteoporosis (2); atrial fibrillation (1); Autoimmunity (1); colon adenocarcinoma (1); Ewing sarcoma (1); glioblastoma (1); hematologic cancer (1); metastatic disease (1); myeloid leukemia (1); pancreatic ductal adenocarcinoma (1); paraganglioma (1); pheochromocytoma (1); rectal adenocarcinoma (1).